ITGB4 (integrin subunit beta 4)
Diseases named in the same sentence as ITGB4 in open-access papers (continued):
Sharing a sentence is not in itself a finding about the gene and the disease.
genetic disorder (1 paper, 2023). "EB-PA is a rare genetic disorder characterized by increased skin fragility and PA involving mutations in the ITGB4, PLEC, or ITGA6 genes." (PMID 37033187, 2023).
hematological cancers (1 paper, 2016). "Studies have shown that FAK signaling pathway is involved in migration and adhesion in human hematological cancers, and the integrin expressed on the cell membrane, such as integrin-β4 (ITGB4), VLA-4 or VLA-5, serves as a critical transducer leading to the activation of FAK signaling." (PMID 26885608, 2016).
inflammation (1 paper, 2020). Aberrant reaction of the microcirculation characterized by movement of fluid and leukocytes from the blood into extravascular tissues. "Here, we further demonstrated that ITGB4 deficiency following birth mediates spontaneous lung inflammation with ILC2 activation and increased infiltration of eosinophils and lymphocytes." (PMID 31970850, 2020). "Since ITGB4 deficiency caused spontaneously pulmonary inflammation and AHR after birth, we further detected whether ITGB4 deficiency influenced pulmonary inflammation and AHR after exposure to HDM in the postnatal period." (PMID 31970850, 2020).
metabolic disorders (1 paper, 2025). "First, what is the relationship among CDKN1A, FOS, ITGB4, and MAP2K1 in metabolic disorders after MI." (PMID 39069811, 2025).
ITGB4 also shares sentences with these, for which no sentence is quoted: lung squamous cell carcinoma (4 papers); chronic pancreatitis (2); head and neck squamous cell carcinoma (2); osteosarcoma (2); renal carcinoma (2); small cell lung carcinoma (2); adenocarcinoma (1); amelogenesis imperfecta (1); anemia (1); basal cell carcinoma (1); breast (1); cataract (1); childhood asthma (1); cutaneous melanoma (1); cystinuria (1); diseases of the nervous system (1); endometrial cancer (1); esophageal squamous cell carcinoma (1); familial Mediterranean fever (1); Human papillomavirus infection (1); hypertrophic cardiomyopathy (1); Hypodontia (1); ichthyosis (1); infarction (1); Junctional epidermolysis bullosa - pyloric atresia (1); liver disease (1); MALT lymphoma (1); medulloblastoma (1); Miscarriage (1); myeloid leukemia (1).
A further 14 diseases each share a sentence with ITGB4 in 1 paper.